MLKL (mixed lineage kinase domain like pseudokinase)
Diseases named in the same sentence as MLKL in open-access papers (continued):
Sharing a sentence is not in itself a finding about the gene and the disease.
cancer (continued). "Among them, the synergy with ferroptosis, further RIPK1/RIPK3/MLKL studies, its association with inflammation and oxidative stress and translational applications, and the therapeutic potential to treat cancer and neurodegenerative diseases are the trending research area." (PMID 35769473, 2022). "Understanding the complex contributions of RIP1-RIP3 and MLKL in human disease is important, as necroptotic cell death has been associated with more than 30 human diseases, including cancer and more than 20 approved drugs have the potential to regulate necroptosis." (PMID 33616081, 2021). "Additionally, it has been found RIP1 and MLKL are both positively associated with cancer parameters including N-cadherin, and suppressing necroptosis inhibited the metastasis of breast cancer." (PMID 34381023, 2021). "In these studies, the authors revealed that decreased expression of MLKL was significantly associated with poor overall survival in cancer patients suggesting a prognostic and clinicopathological significance of expression level of MLKL in cancer patients." (PMID 32917855, 2020). "However, after excluding this study, we still observed that decreased expression level of MLKL was significantly associated with poor OS in cancer patients." (PMID 30005626, 2018). "In addition, the expression of Cox-2 and iNOS, two major inflammatory mediators implicated in colorectal inflammation and cancer, were enhanced in MLKL−/− mice." (PMID 29456533, 2018). "A better understanding of the complex and potentially opposing functions of MLKL, associated necroptosis and their demarcation to other forms of regulated cell death in cancer will be needed for therapeutic exploitation of these pathways to the benefit of patients with cancer." (PMID 40345706, 2025). "Therefore, we propose that NMR-specific loss-of-function mutations in the necroptosis regulators RIPK3 and MLKL may be one of the mechanisms underlying the attenuated tissue inflammatory response and remarkable cancer resistance of NMRs." (PMID 35354912, 2022). "The downregulated MLKL expression could lead to inhibition of the necroptotic phenomenon and therefore determine a poor prognosis underlying its role as prognostic biomarker in cancer." (PMID 33567618, 2021). "Given the pivotal role of MLKL in necroptosis, one possible underlying mechanism for the association between low MLKL expression levels with poor prognosis of cancer patients may be the result of decreased necroptosis signaling, leading to the resistance to death for cancer cells in these patients." (PMID 30005626, 2018). "Based on its regulatory functions on the organelles, MLKL is involved in or even contributes to the occurrence and development of multiple conditions, including cancer, neurological, metabolic, cardiovascular, and respiratory diseases." (PMID 40070567, 2025). "This controlled activation of MLKL offers a targeted approach for modulating antitumoral immunity, presenting significant promise for advancing cancer therapy strategies." (PMID 39921454, 2025). "Necroptosis, a regulated form of necrotic cell death mediated by receptor-interacting protein kinases RIPK1 and RIPK3, and the pseudokinase MLKL, has emerged as a potential alternative pathway to induce cancer cell death." (PMID 41303584, 2025). "We found that MLKL inactivation when combined with a clinically approved anti-cancer drug HHT represents an effective approach for killing CRC cells in vitro and suppressing their tumorigenicity in vivo." (PMID 39979285, 2025). "In HeLa, H2009, and MDA-MB231 cancer cells, MLKL enhances cancer cell death by increasing endocytosis and endosomal trafficking of TRAIL-DR5 apoptotic signals compared to control cells." (PMID 40070567, 2025). "Key necroptotic regulators like RIPK1, RIPK3, and MLKL are often altered in cancer, allowing cells to evade necroptosis." (PMID 40893939, 2025).
cancer (continued). "In BMDCs, we found upregulation of the costimulatory molecule CD86 upon interaction with necroptotic MOC1 cells which was dependent on active RIPK3 and MLKL in carcinoma cells and was blocked by necrostatin-1." (PMID 40345706, 2025). "When used alone, neither of these inhibitors significantly affected the level of phospho-MLKL in either cancer cell lines compared to the untreated controls." (PMID 39062543, 2024). "The up-regulation of MLKL is presumed to sensitize cancer cells to necroptotic cell death, and pronecroptotic therapy is potentially effective for cancer cells that highly express MLKL." (PMID 38474369, 2024). "RIPK3, a member of the receptor interacting protein kinase family, interacts with RIPK1 to form necroptotic complexes, activating MLKL and initiating necroptosis, thereby repressing cancer development." (PMID 38877579, 2024). "The STAT1-IRF1 pathway transcriptionally promotes MLKL expression in multiple types of cancer cell lines in response to interferon-γ." (PMID 38474369, 2024). "While substitutions at R30 of MLKL have not been reported in ClinVar or the Catalogue of Somatic Mutations in Cancer (COSMIC), the R30E mutation was selected as an experimental tool to dissect mechanisms of downstream MLKL signalling." (PMID 39136677, 2024). "Research on polychlorinated biphenyl (PCB) toxicity has demonstrated that PCB-induced necroptosis in cancer cells enhances exosome synthesis and release through MLKL phosphorylation MLKL." (PMID 38424607, 2024). "Low MLKL expression levels have been detected in multiple cancer cell lines and several cancer types." (PMID 38213773, 2024). "Additionally, RIP1 and RIP3 expressions in cancer cells are inclined to be decreased because of genetic mutations or hypoxic induction; thus, pharmaceutical companies may develop new agents that directly target and activate MLKL." (PMID 38994937, 2024). "Existing studies have established the propensity of DNA-damaging chemotherapeutic agents to invoke necroptosis, thereby instigating cancer cell demise via the RIP1/RIP3/MLKL pathway." (PMID 38036577, 2023). "This evidence supports the notion that cellular environmental cues, such as infection, tissue injury, inflammation, and cancer, result in a higher expression of MLKL." (PMID 37373257, 2023). "Next, we evaluated the relationship between the copy number variations of RIPK3 and MLKL, the key genes of necroptosis in pan-cancer, and the levels of immune infiltration of different immune cells using the TIMER database." (PMID 37000317, 2023). "As an effector of necroptosis, MLKL is transcriptionally up-regulated by IFNs in cancer cells, leading to a higher level of MLKL that sensitizes cells towards necroptosis." (PMID 37532777, 2023). "RIPK1 is highly expressed in KIRC and is upregulated by TNF-α, which further induces necrotic apoptosis of cancer cells through the RIPK1/RIPK3/MLKL/Drp1 axis." (PMID 37847185, 2023). "In this regard, it has been shown that MLKL is transcriptionally upregulated by interferons in different types of cells, such as cancer cells, lung epithelial cells, and bone-marrow-derived macrophages in response to inflammatory stimuli." (PMID 37373257, 2023). "Research has also shown that decreased MLKL expression decreases the overall survival and leads to poor prognosis in different types of cancer." (PMID 35359956, 2022). "Relative expressions of RIPK1, RIPK3, and MLKL proteins were significantly (0.001) elevated in both HepG2 and A549 cancer cells after treatment with the IC50 of the CM derivative, when compared to the untreated cells." (PMID 36432094, 2022). "Previous studies have shown that RIPK3, RIPK1, and MLKL are the most important factors involved in necroptotic, playing important roles during cancer progression." (PMID 36110223, 2022). "Among them, MLKL was highly expressed in cancer tissues, while RIPK1 and RIPK3 were lowly expressed in cancer tissues." (PMID 36544770, 2022).
cancer (continued). "Although activation of MLKL is the executor of the necroptotic process, the expression of MLKL varies much across cancers, which is related to its complex cytological function." (PMID 36506314, 2022). "In summary, our results demonstrated that IDOAMP inhibited Aurora kinase A, promoting the RIPK1/RIPK3/MLKL necrosome activation to antiprostate cancer." (PMID 35965682, 2022). "For instance, the knockout of the necroptosis key molecules such as RIPK1, RIPK3, or MLKL in cancer cells markedly reduced tumorigenicity." (PMID 36505813, 2022). "Necroptosis is a programmed cell death mode mediated by three major mediators, RIPK1, RIPK3, and MLKL, and has been shown to play a role in various cancers." (PMID 35965497, 2022). "Though lacking any catalytic activity, MLKL has retained its ability to bind nucleotides and it has been found that ATP-binding to MLKL as well as MLKL PsKD mutants, including some identified in cancers, stabilized the monomeric OFF state." (PMID 35938171, 2022). "Increasing evidence shows that necroptosis contributes to the pathology of many severe diseases 97, especially inflammation and cancer, and numerous researchers have attempted to develop drugs to block MLKL function." (PMID 33754026, 2021). "Several recent reports indicated that the lower levels of MLKL were correlated with poor overall survival in malignant tumors 12, 49-52." (PMID 33767595, 2021). "MLKL, the molecular executioner of necroptosis, has also been also found to be downregulated in several types of cancer." (PMID 34490126, 2021). "Dysregulation of RIPK3 and MLKL levels, and inactivation of this inflammatory cell-death pathway, is commonly seen in numerous cancers (e.g.7–9)." (PMID 32393742, 2020). "A reduction in MLKL expression in cancer cells would therefore be expected to result in enhanced TRAIL-induced therapeutic efficacy." (PMID 32917855, 2020). "While RIPK1, which acts in concert with RIPK3 to form fibrils and phosphorylate MLKL, is consistently preserved in cancers because it is also required for the operation of the TNF/TNFR1/NF-κB signaling axis." (PMID 32393742, 2020). "In this study, we found that depletion of MLKL accelerates TRAIL-induced cancer cell apoptosis, and that enhancement of such cell death by MLKL depletion occurs via a RIP3-independent manner." (PMID 32917855, 2020). "We, therefore, investigated the endosomal trafficking function of MLKL on TRAIL-induced cell death in cancer cells." (PMID 32917855, 2020). "In this study, we investigated the effects of the endosomal trafficking functions of MLKL on TRAIL-induced cell death in cancer cells." (PMID 32917855, 2020). "RIPK3 and MLKL expression seems to vary among tissue samples from different subtypes and stages of cancer, and downregulation of necroptosis mediators has also been published in various cancers." (PMID 31719524, 2019). "A total of three studies including 368 patients reported the impact of abnormally expressed MLKL on DFS or RFS of cancer patients." (PMID 30005626, 2018). "This is the first meta-analysis to evaluate the relationship between expression levels of MLKL, the critical component in necroptosis pathway, with prognosis of cancer patients." (PMID 30005626, 2018). "To understand how changes in the PsKD of MLKL control the transition between monomer and tetramer, we introduced a series of mutations into full-length hMLKL guided by XL-MS, HDX-MS, and residues mutated in human cancer specimens." (PMID 29930286, 2018). "Using HRs of Cox multivariate analysis from three studies, we found that decreased MLKL expression was an independent prognostic factor for OS in cancer patients (HR = 0.31, 95%CI: 0.17–0.54, p < 0.001)." (PMID 30005626, 2018). "In conclusion, our study revealed that decreased expression level of MLKL was significantly associated with poor OS and EFS in cancer patients." (PMID 30005626, 2018).
cancer (continued). "A total of 6 studies involving 613 patients reported the relationship between abnormal expression levels of MLKL with OS of cancer patients." (PMID 30005626, 2018). "We demonstrate that genetic knockout of necroptotic genes RIPK1, RIPK3, or MLKL in cancer cells significantly attenuated their abilities to grow in an anchorage-independent manner." (PMID 26959742, 2016). "Nonetheless, our overall data and message still point to the fact that CD47 blockade could consistently induce MLKL-dependent necroptotic-cell death across a broad array of cancer cell lines and xenograft models." (PMID 41484790, 2026). "Altogether, our data suggest that MLKL in LPCs contributes to HCC initiation in the context of MASH, potentially involving its described non-canonical role within mitochondria, promoting oxidative stress, a cancer hallmark." (PMID 41708607, 2026). "Thus, for future MLKL-based therapies, it is crucial to assess the expression patterns and opposing functions of MLKL across a broad range of cancers before considering its exploitation in anti-cancer therapies." (PMID 40691738, 2025). "For instance, why do some cancer cells exhibit MLKL‐dependent necroptosis while others evade it?" (PMID 40788062, 2025). "Activated MLKL serves as the key executor of necroptosis, and its upregulation or activation has been shown to play a role in neurological, respiratory and cardiovascular diseases, as well as various types of cancer." (PMID 40563424, 2025). "Only the level of this latter form of activated MLKL correlated with the number of dying, annexin-positive cancer cells in the previous study, which suggests that such structures represent the phospho-MLKL oligomers that are responsible for the execution of necroptosis." (PMID 39062543, 2024). "Additionally, under the effects of SMAC mimics (including SM164) and pan-caspase inhibitors (including Z-VAD-FMK), RIPK3 can interact with RIPK1 to form necrosomes, leading to the phosphorylation of MLKL and necroptosis of cancer cells." (PMID 38684668, 2024). "Additionally, knocking out essential necroptosis factors like RIP1, RIP3, or MLKL can significantly inhibit cancer cell proliferation in vitro and reduce their ability to form tumors in vivo." (PMID 38994937, 2024). "Moreover, complementary therapies such as heat therapy and antihypoxia therapy, or the development of MLKL agonists used in combination with necroptotic cancer therapy, hold potential in overcoming resistance to necroptosis." (PMID 38994937, 2024). "Its upregulation in response to inflammation and tissue injury suggests that MLKL may play dual roles in cancer." (PMID 39439891, 2024). "MLKL expression in cancer tissues was significantly higher than that in adjacent normal tissues." (PMID 36650126, 2023). "Necroptosis is a caspase-independent and regulated cell death mechanism which primarily mediated by receptor-interacting kinase (RIPK) and mixed lineage kinase domain-like protein (MLKL) that has been connected to the formation and progression of many cancers and inflammatory illnesses." (PMID 37663658, 2023). "The role of MLKL in cancer is still puzzling, as necroptosis could have both antitumorigenic and pro-tumorigenic roles." (PMID 37373257, 2023). "Furthermore, we found that metformin/efavirenz/fluoxetine combination caused increases of necroptosis-related proteins (such as MLKL, p-MLKL, RIP3, and p-RIP3) in treated HCT116 cancer cells." (PMID 36588385, 2023). "Interestingly, it has been found that necrosome-related genes (such as RIPK1, RIPK3, or MLKL) experience unspecific genetic deletions at the same rate as background genetic aberration frequency, seen in cancers." (PMID 37628814, 2023). "Therefore, inducing necroptosis by activating key regulators of necroptosis, including RIPK1, RIPK3 and MLKL, has emerged as a promising option for therapy for different cancers, including EC." (PMID 37564206, 2023).
cancer (continued). "Additionally, MLKL expression was positively correlated with the level of all immune cell infiltration in most cancer types." (PMID 37000317, 2023). "In fact, the suppression of MLKL is important for cancer cell survival and metastasis." (PMID 38137900, 2023). "Many key necroptosis factors are downregulated in cancer, including RIPs, MLKL, CYLD, and FADD." (PMID 35359956, 2022). "On the one hand, the downregulation of the expression of numerous key molecules in necroptosis such as RIPK1, RIPK3, and MLKL has been found in different types of cancer cells, suggesting that cancer cells may evade necroptosis to survive." (PMID 36505813, 2022). "Unfortunately, the exact role of MLKL in cancer progression and metastasis is still unclear." (PMID 36506314, 2022). "Recent literature suggests that multiple functions of MLKL beyond necroptosis might determine the therapeutic outcome pending on cancer types and stages." (PMID 35422482, 2022). "However, the expression of RIPK3 and MLKL is reduced in various cancer cells, including breast cancer, colorectal cancer, acute myeloid leukemia, and nonsmall cell lung cancer." (PMID 39872161, 2022). "The hypermethylation of the same necroptosis-related regulator could have different effects on prognosis in different cancer types, such as MLKL in LGG and SKCM." (PMID 35748782, 2022). "Survival analysis showed that CNVs of TNF in 22 cancer types, TLR3 in 10 cancer types, RIPK1 in 9 cancer types, FAS in 8 cancer types, FADD in 8 cancer types, RIPK3 in 7 cancer types, MLKL in 6 cancer types, and FASLG in 5 cancer types were significantly associated with overall prognosis." (PMID 35748782, 2022). "Moreover, cBioPortal analyses of the TCGA database 28 showed a significant co-occurrence (p=0.002) of genomic alterations of MLKL (mainly deep deletion and mutation) and BCL2L1 (BCL-x) (mainly amplification) in pan-cancer cohorts (32 studies, 10967 patients)." (PMID 33531997, 2021). "In addition to RIPK1, the necroptotic mediators RIPK3 and MLKL are also involved in cancer and have influence on prognosis." (PMID 33567618, 2021). "Neglecting the novel functions of MLKL could potentially lead to serious side-effects if MLKL inhibitors are used for the treatment of inflammation or cancer in humans." (PMID 33754026, 2021). "Another study showed that suppressing EMT was one effective way to inhibit invasion of radioresistant cancers, and inhibition of necroptosis such as depleting MLKL expression suppresses invasion of radioresistant nasopharyngeal carcinoma cells by suppressing EMT." (PMID 34381023, 2021). "Whereas, if MLKL expression is upregulated dramatically, necroptosis may also be induced in cancer cells, which results in cell death." (PMID 33754026, 2021). "Here, we report for the first time that the key necroptotic proteins RIPK1, RIPK3 and MLKL, which have been reported to be lost or harbor reduced expression in other cancers, were expressed in both CCA primary tissues (TCGA database) and a panel of CCA cell lines." (PMID 31914150, 2020). "In situations in which a functional caspase-8 is deficient, SMs were reported to trigger the production of necrosome, consisting of RIP1, receptor-interacting protein kinase 3 (RIP3), and mixed lineage kinase domain-like (MLKL), thereby promoting cancer cells to undergo TNFα-stimulated necroptosis." (PMID 32325691, 2020). "Importantly, MLKL (mixed lineage kinase domain-like protein) inhibitor necrosulfonamide exerted a synergistic effect by increasing the sensitivity of cancer cells to GA." (PMID 31455047, 2019). "MLKL also plays pivotal roles in the pathogenesis of cancer." (PMID 30005626, 2018). "The subgroup analysis illustrated the same results that the significant association between decreased expression levels of MLKL with poor OS of cancer patients was not altered with all the factors above." (PMID 30005626, 2018).